POPDC3 (popeye domain cAMP effector 3)
Description:
May play a role in the maintenance of heart function mediated, at least in part, through cAMP-binding. May play a role in the regulation of KCNK2/TREK-1-mediated current amplitude.
Synonyms: POP3; MGC22671; bA355M14.1; LGMDR26
Tractability: Antibody: UniProt predicts a signal peptide or a membrane-spanning region; its Gene Ontology location is reachable by antibodies, with medium confidence.
Gene: Protein-coding gene on chromosome 6 (105,157,892 to 105,180,447, reverse strand). Ensembl gene ENSG00000132429.
Subcellular location: Membrane
Subcellular location (Human Protein Atlas): Cytosol; Nucleoli
Gene Ontology:
Molecular function: protein binding; cAMP binding
Biological process: heart development; regulation of membrane potential; skeletal muscle tissue development; striated muscle cell differentiation
Cellular component: membrane; sarcolemma
Genetic constraint (gnomAD): Loss-of-function variants: 18 observed, 26.17 expected, observed/expected ratio (o/e) 0.69, 90% interval 0.47 to 1.02. The upper end of that interval is the gene's LOEUF score, 1.02, which puts it in group 4 of 6, group 1 being the genes least tolerant of losing a copy. Missense variants: 301 observed, 350.53 expected, observed/expected ratio (o/e) 0.86, 90% interval 0.78 to 0.94. Synonymous variants: 113 observed, 126.11 expected, observed/expected ratio (o/e) 0.9, 90% interval 0.77 to 1.05.
Gene-disease validity (ClinGen):
ClinGen rates the evidence that POPDC3 causes each of these diseases.
autosomal recessive limb-girdle muscular dystrophy (autosomal recessive): Definitive. Autosomal recessive form of limb-girdle muscular dystrophy.
Homologues: Orthologues: chimpanzee POPDC3 (100% identical), macaque POPDC3 (99% identical), rabbit POPDC3 (97% identical), dog POPDC3 (96% identical), pig POPDC3 (95% identical), guinea pig POPDC3 (91% identical), rat Popdc3 (90% identical), mouse Popdc3 (89% identical), zebrafish popdc3 (56% identical), Drosophila melanogaster bves (24% identical). Paralogues in human: POPDC2 (47% identical), POPDC1 (30% identical).
Diseases named in the same sentence as POPDC3 in open-access papers:
POPDC3 is named in the same sentence as 18 diseases in open-access papers, as found by Europe PMC text mining. Sharing a sentence is not in itself a finding about the gene and the disease. The quoted sentences say what the papers report.
gastric cancer (4 papers, 2019 to 2022). A primary or metastatic malignant neoplasm involving the stomach. "Besides, low expression of POPDC3 was also reported to be associated with metastasis and poor prognosis of gastric cancers." (PMID 34432380, 2021). "However, the suppression of POPDC3 has also been linked to oncogenic functions in gastric cancer." (PMID 31817925, 2019). "Recent studies have shown that the expression level of POPDC3 is closely related to the cell proliferation, metastasis and prognosis of a variety of cancers, especially gastric cancer, and can be used as a potential cancer treatment target." (PMID 36713522, 2022). "POPDC1 and POPDC3 downregulation was described in several tumors, including colon and gastric cancers." (PMID 34069715, 2021). "For example, researchers found that knockdown of POPDC3 significantly increased the migration and invasion of gastric cancer cells." (PMID 34432380, 2021). "Hypermethylation of the POPDC3 promoter is thus thought to be a potential mechanism by which long-term POPDC3 suppression is maintained in gastric cancer." (PMID 31817925, 2019). "Given that POPDC3 demonstrates potential tumor suppressor roles in gastric cancer while also correlating with oncogenic roles in breast cancer and head and neck carcinoma, the effects of POPDC3 are likely to be tissue-specific." (PMID 31817925, 2019). "In a study that assessed POPDC3 expression in gastric cancer tissues, reduced expression levels of POPDC3 correlated with the depth of invasion, regional lymph node and distant metastasis as well as poor prognosis." (PMID 31817925, 2019). "In addition, low POPDC3 expression has also been correlated to metastasis and high depth of invasion in gastric cancer." (PMID 31817925, 2019). "Furthermore, the epigenetic inactivation of POPDC3 via promoter hypermethylation has also been reported in gastric cancer tissues." (PMID 31817925, 2019). "Although the effects of POPDC2 and POPDC3 on cell migration, invasion and metastasis have not been extensively studied, the suppression of POPDC3 has been shown to stimulate cell migration and invasion in gastric carcinoma cells." (PMID 31817925, 2019).
limb-girdle muscular dystrophy (4 papers, 2019 to 2025). Limb-girdle muscular dystrophy (LGMD) is a heterogeneous group of muscular dystrophies characterized by proximal weakness affecting the pelvic and shoulder girdles. "Mutations in POPDC1, POPDC2 and POPDC3 have been recently identified in patients suffering from cardiac arrhythmia and/or limb-girdle muscular dystrophy, respectively." (PMID 34999055, 2022). "In contrast, patients carrying mutations in POPDC3 display a severe limb-girdle muscular dystrophy (LGMDR26) but a normal heart." (PMID 34940515, 2021). "The three recently reported pathological mutations in POPDC3 (L155H, L217F and R261Q), which were discovered in patients suffering from limb-girdle muscular dystrophy show variability in their effect on cAMP binding." (PMID 31817925, 2019). "Unlike the recessive syndrome associated with the other POPDC genes (i.e., POPDC1 and POPDC3-related limb-girdle muscular dystrophy), none of the affected individuals showed signs of muscular dystrophy." (PMID 40409267, 2025). "Although it is currently not known whether POPDC2 and POPDC3 also bind PDE4, mutation of leucine 155 to histidine in POPDC3, which corresponds to leucine 173 in POPDC1, was recently identified in a patient suffering from limb-girdle muscular dystrophy (LGMDR26, OMIM 605824)." (PMID 34999055, 2022).
breast carcinoma (3 papers, 2013 to 2025). "In a recent study that examined the expression of POPDC proteins in ductal breast carcinoma, POPDC2 and POPDC3 were found to be significantly overexpressed in breast cancer tissues." (PMID 31817925, 2019). "Enhanced expression of POPDC2 was observed at all clinical stages of breast cancer while POPDC3 was only expressed at higher levels in early stages of the disease." (PMID 31817925, 2019). "Elevated POPDC3 expression in breast cancer is significantly correlated with HER2+ status." (PMID 39971925, 2025). "Overall, this data suggests potential oncogenic roles of POPDC2 and POPDC3 in breast cancer with POPDC3 potentially only involved in initiating breast tumorigenesis, while POPDC2 seems to be involved in initiating and sustaining breast cancer at all clinical stages." (PMID 31817925, 2019).
cardiac arrhythmia (3 papers, 2023 to 2025). Any disturbances of the normal rhythmic beating of the heart or MYOCARDIAL CONTRACTION. "Patients carrying POPDC2 variants show only cardiac arrhythmias, while POPDC3 variants are only associated with LGMD." (PMID 36624536, 2023).
head and neck squamous cell carcinoma (3 papers, 2019 to 2025). A squamous cell carcinoma that arises from any of the following anatomic sites: lip and oral cavity, nasal cavity, paranasal sinuses, pharynx, larynx, and salivary glands. "In contrast, a recent study found that high POPDC3 expression was significantly associated with poor prognosis in head and neck squamous cell carcinoma." (PMID 34432380, 2021). "The potential oncogenic functions of POPDC3 were further demonstrated in head and neck squamous cell carcinoma (HNSCC) where high POPDC3 expression levels correlated with poor patient survival." (PMID 31817925, 2019). "However, high POPDC3 expression has also been correlated to poor clinical prognosis in head and neck squamous cell carcinoma, suggesting that POPDC3 potentially plays different roles in the progression of different types of cancer." (PMID 31817925, 2019). "In head and neck squamous cell carcinoma (HNSCC), lower POPDC3 expression correlates with longer overall survival." (PMID 39971925, 2025).
muscular dystrophy (3 papers, 2022 to 2025). Muscular dystrophy (MD) refers to a group of more than 30 genetic diseases characterized by progressive weakness and degeneration of the skeletal muscles that control movement. "Indeed, POPDC2 is predominantly expressed in cardiac tissue, whereas POPDC3, which presents with isolated muscular dystrophy, has a predominant expression in skeletal muscle." (PMID 40409267, 2025). "We then conducted genetic burden analyses, wherein rare variants in POPDC2 are aggregated, with the phenotypes above and muscular dystrophy as this is a clinical hallmark of recessive syndromes associated with the two other members of the POPDC family (i.e., POPDC1 and POPDC3)." (PMID 40409267, 2025). "Bi-allelic variants in POPDC1 and POPDC3 have been associated with muscular dystrophy, with and without CCD, respectively, while the affected individuals reported here presented with isolated cardiac disease." (PMID 40409267, 2025). "In addition, research on POPDC3 covers topics including muscular dystrophy, cardiac function and other aspects; research on POPDC3 in NB is lacking, but this is a topic worthy of in-depth exploration." (PMID 36713522, 2022).
Lewis lung carcinoma (1 paper, 2025). "Moreover, ectopic POPDC3 overexpression in C57BL/6 J mouse Lewis lung carcinoma (LLC) xenografts enhanced CD4+ T cell infiltration and PD-1 expression in the TME." (PMID 39971925, 2025).
lung adenocarcinoma (1 paper, 2025). A carcinoma that arises from the lung and is characterized by the presence of malignant glandular epithelial cells. "IHC analysis of POPDC3 was conducted on two NSCLC tissue microarrays (TMAs), comprising 90 samples of lung adenocarcinoma (LUAD) and 90 samples of lung squamous cell carcinoma (LUSC), along with corresponding adjacent non-cancerous tissue samples." (PMID 39971925, 2025).
lung carcinoma (1 paper, 2019). "In addition, an upregulation of POPDC3 was also reported in radioresistant esophageal and lung cancer, suggesting that potentially POPDC3 serves a role in acquired radiotherapy resistance." (PMID 31817925, 2019).
nasopharyngeal carcinoma (1 paper, 2025). A carcinoma arising from the nasopharyngeal epithelium. "Furthermore, decreased POPDC3 expression in radiation-resistant nasopharyngeal carcinoma tissues correlates with lower progression-free survival." (PMID 39971925, 2025).
NK/T cell lymphoma (1 paper, 2015). "The deletion of 6q21 has been identified as the common genetic aberration in NK/T cell lymphoma (20–43%), and the genes located in the region of 6q21, including POPDC3, PREP, PRDM1, ATG5, AIM1, HACE1, and FOXO3, were reasonably considered the affected candidates." (PMID 26221594, 2015).
tumor (6 papers, 2013 to 2025). "The association of POPDC1 and POPDC3 downregulation with IM-to-GC transition implicates a role in tumor suppression and highlights them as potential biomarkers for GC progression and prospective treatment targets." (PMID 34069715, 2021). "The association of POPDC1 and POPDC3 downregulation with IM and GC suggests a role in tumor suppression and highlights them as potential biomarkers for IM and GC progression and as prospective treatment targets." (PMID 34069715, 2021). "Although this study only established a correlation between POPDC3 expression and cancer progression, causality between loss of POPDC3 function and enhanced tumor cell migration has also been established." (PMID 31817925, 2019). "In contrast to POPDC1, POPDC2 and POPDC3, have been associated with both oncogenic and tumor suppressor roles in different cancer types suggesting that these proteins might serve tissue-specific functions." (PMID 31817925, 2019). "Analysis of fresh tumor tissue lysates revealed substantial reductions in POPDC3 mRNA and protein levels in sh-POPDC3 xenografts, while the mRNA levels of POPDC1 and POPDC2 remained unchanged." (PMID 39971925, 2025). "Our research further reveals that upregulation of POPDC3 is associated with increased CD4+ T cell infiltration and elevated PD-1 expression in NSCLC tissues, suggesting a possible interplay between tumor malignancy and the immune response." (PMID 39971925, 2025). "Ultimately, this could inform the development of targeted therapeutic strategies that take into account the nuanced functions of POPDC3 in tumor progression and metastasis." (PMID 39971925, 2025). "POPDC1 and POPDC3 likely function as tumor suppressors and the reported inverse relationship between POPDC1 levels and c-Myc expression and Wnt signaling may link POPDC1 underexpression to intestinal stem cell programming and malignant tumor growth." (PMID 34069715, 2021). "Although we have not directly assessed the efficacy of immunotherapy in this context, our findings indicate a relationship between tumor POPDC3 expression, PD-1-positive CD4+ T cell infiltration, and potential T cell exhaustion, which could inform future studies on immunotherapy responsiveness." (PMID 39971925, 2025). "To further investigate the role of POPDC3, identified as a key LRG, in modulating immune responses within the tumor microenvironment, we employed multiplex immunohistochemistry (mIHC)." (PMID 39971925, 2025). "Our findings provide new insights into the interaction between LR dynamics and NSCLC, highlighting the significance of popeye domain-containing protein 3 (POPDC3) in promoting immune evasion and tumor progression." (PMID 39971925, 2025). "Analysis of fresh tumor tissue lysates revealed the mRNA levels of POPDC1 and POPDC2 remained unchanged, but there was a substantial upregulation in POPDC3 mRNA and protein levels in POPDC3-OE priNSCLC-1 xenografts." (PMID 39971925, 2025). "We found inverse correlation between the expression of mucins that characterize severity of malignant transformation, and the tumor suppressors POPDC1 and POPDC3, suggesting an inverse regulatory linkage." (PMID 34069715, 2021). "This study showed that BIRC5, SLCO4A1, POPDC3, and HK2 were significantly downregulated in stage MS NB and affected the survival rate of children, indicating that the low expression of these four genes is a factor conducive to tumor regression." (PMID 36713522, 2022). "Unlike its isoform POPDC1 which acts as a tumor suppressor, POPDC3 has been found to play distinct roles in different cancer types." (PMID 34432380, 2021).
cancer (5 papers, 2019 to 2025). A tumor composed of atypical neoplastic, often pleomorphic cells that invade other tissues. "Uncovering the molecular mechanism that underly the divergence in POPDC3 function in different tissues will provide better insight on how the protein could be targeted in different cancers." (PMID 31817925, 2019). "Moreover, downregulation of POPDC1 and POPDC3 expression in different cancer types has been associated with poor prognosis." (PMID 31817925, 2019). "This suggests that the roles of POPDC2 and POPDC3 might differ in different cancers while POPDC1 potentially regulates cell proliferation in a similar manner in different tissues." (PMID 31817925, 2019). "Investigating the roles and mechanisms by which POPDC2 and POPDC3 potentially regulate migration, invasion and metastasis will also provide the much-needed clarity on how diverse the functions of POPDC proteins might be in various cancer types." (PMID 31817925, 2019).
genetic disorders (1 paper, 2025). "Human genetic disorders associated with POPDC3 variants highlight the importance of POPDC3 in the maintenance of skeletal muscle mass and function." (PMID 40237439, 2025).
POPDC3 also shares sentences with these, for which no sentence is quoted: cardiac disease (1 paper); head and neck carcinoma (1); lung squamous cell carcinoma (1); non-small cell lung carcinoma (1).